OR4C15 (olfactory receptor family 4 subfamily C member 15)
Description:
Odorant receptor.
Synonyms: OR11-127; OR11-134
Tractability: Antibody: UniProt places it where antibodies can reach, with medium confidence; UniProt predicts a signal peptide or a membrane-spanning region; its Gene Ontology location is reachable by antibodies, with medium confidence.
Gene: Protein-coding gene on chromosome 11 (55,554,307 to 55,555,419, forward strand). Ensembl gene ENSG00000181939.
Subcellular location: Cell membrane
Pathways (Reactome):
Sensory Perception: Expression and translocation of olfactory receptors
Gene Ontology:
Molecular function: olfactory receptor activity; G protein-coupled receptor activity
Biological process: detection of chemical stimulus involved in sensory perception of smell; G protein-coupled receptor signaling pathway
Cellular component: plasma membrane; membrane
Genetic constraint (gnomAD): Loss-of-function variants: 0 observed, 0.12 expected, observed/expected ratio (o/e) 0, 90% interval 0 to 1.89. That is too few expected variants to judge how well the gene tolerates losing a copy. Missense variants: 697 observed, 397.72 expected, observed/expected ratio (o/e) 1.75, 90% interval 1.65 to 1.87. Synonymous variants: 216 observed, 141.61 expected, observed/expected ratio (o/e) 1.53, 90% interval 1.36 to 1.71.
Homologues: Orthologues: chimpanzee OR4C15 (99% identical), mouse Or4c15 (82% identical), rat Or4c15 (81% identical), mouse Or4c15b (79% identical), rat Or4c15b (78% identical), mouse Or4c124 (75% identical), mouse Or4c107 (73% identical), rat Or4c107 (73% identical), rat Or4c124b (73% identical), mouse Or4c118 (73% identical), mouse Or4c108 (72% identical), rat Or4c116 (72% identical), and 28 more. Paralogues in human: OR4C46 (63% identical), OR4C13 (61% identical), OR4C3 (61% identical), OR4C6 (58% identical), OR4C12 (58% identical), OR4A5 (57% identical), OR4C11 (57% identical), OR4A15 (56% identical), OR4S2 (56% identical), OR4C45 (55% identical), OR4X2 (55% identical), OR4A8 (54% identical), and 116 more.